ITGA3 (integrin subunit alpha 3)
Description:
Integrin alpha-3/beta-1 is a receptor for fibronectin, laminin, collagen, epiligrin, thrombospondin and CSPG4. Integrin alpha-3/beta-1 provides a docking site for FAP (seprase) at invadopodia plasma membranes in a collagen-dependent manner and hence may participate in the adhesion, formation of invadopodia and matrix degradation processes, promoting cell invasion. Alpha-3/beta-1 may mediate with LGALS3 the stimulation by CSPG4 of endothelial cells migration. (Microbial infection) Integrin ITGA3:ITGB1 may act as a receptor for R.delemar CotH7 in alveolar epithelial cells, which may be an early step in pulmonary mucormycosis disease progression.
Synonyms: GAPB3; CD49c; MSK18; VLA3a; VCA-2; GAP-B3; FRP-2; ILNEB; JEB7; VL3A
Tractability: Antibody: UniProt places it where antibodies can reach, with high confidence; its Gene Ontology location is reachable by antibodies, with high confidence; UniProt predicts a signal peptide or a membrane-spanning region; the Human Protein Atlas places it where antibodies can reach. PROTAC: ubiquitination databases record sites on it; its protein half-life has been measured; a small molecule that binds it is known.
Target class: Membrane receptor
Gene: Protein-coding gene on chromosome 17 (50,055,968 to 50,090,485, forward strand). Ensembl gene ENSG00000005884.
Subcellular location: Cell membrane; Cell projection, invadopodium membrane; Cell projection, filopodium membrane
Subcellular location (Human Protein Atlas): Plasma membrane
Pathways (Reactome):
Extracellular matrix organization: Integrin cell surface interactions; Laminin interactions
Hemostasis: Basigin interactions
Signal Transduction: MET activates PTK2 signaling
Gene Ontology:
Molecular function: protease binding; protein binding; protein heterodimerization activity; signaling receptor activity
Biological process: lung development; mesodermal cell differentiation; nephron development; positive regulation of protein localization to plasma membrane; regulation of BMP signaling pathway; regulation of transforming growth factor beta receptor signaling pathway; regulation of Wnt signaling pathway; renal filtration; skin development; cell-cell adhesion; cell-matrix adhesion; dendritic spine maintenance; exploration behavior; integrin-mediated signaling pathway; leukocyte migration; negative regulation of Rho protein signal transduction; cell adhesion; cell differentiation; postsynapse organization; regulation of signal transduction; synaptic membrane adhesion; system development; system process
Cellular component: cell periphery; cell surface; extracellular exosome; filopodium membrane; focal adhesion; integrin alpha3-beta1 complex; plasma membrane; receptor complex; excitatory synapse; integrin complex; synaptic membrane; basolateral plasma membrane; external side of plasma membrane; glutamatergic synapse; neuromuscular junction; presynaptic active zone membrane; synapse
Genetic constraint (gnomAD): Loss-of-function variants: 64 observed, 114.22 expected, observed/expected ratio (o/e) 0.56, 90% interval 0.46 to 0.69. The upper end of that interval is the gene's LOEUF score, 0.69, which puts it in group 2 of 6, group 1 being the genes least tolerant of losing a copy. Missense variants: 1,039 observed, 1,306.9 expected, observed/expected ratio (o/e) 0.8, 90% interval 0.75 to 0.84. Synonymous variants: 518 observed, 542.29 expected, observed/expected ratio (o/e) 0.96, 90% interval 0.89 to 1.03.
Gene-disease validity (ClinGen):
ClinGen rates the evidence that ITGA3 causes each of these diseases.
epidermolysis bullosa, junctional 7, with interstitial lung disease and nephrotic syndrome (autosomal recessive): Definitive. A life-threatening multiorgan disorder which develops in the first months of life, presenting with respiratory distress and proteinuria in the nephrotic range, and leading to severe interstitial lung disease and renal failure.
Homologues: Orthologues: chimpanzee ITGA3 (97% identical), macaque ITGA3 (96% identical), dog ITGA3 (88% identical), guinea pig ITGA3 (87% identical), mouse Itga3 (87% identical), pig ITGA3 (87% identical), rat Itga3 (85% identical), rabbit ITGA3 (83% identical), tropical clawed frog itga3 (54% identical), zebrafish itga3b (45% identical), zebrafish itga3a (41% identical), Drosophila melanogaster mew (29% identical), and 6 more. Paralogues in human: ITGA7 (37% identical), ITGA6 (37% identical), ITGA5 (24% identical), ITGAV (24% identical), ITGA8 (24% identical), ITGA2B (24% identical), ITGA4 (22% identical), ITGA1 (22% identical), ITGA9 (22% identical), ITGA10 (22% identical), ITGA2 (22% identical), ITGAM (21% identical), and 5 more.
Diseases named in the same sentence as ITGA3 in open-access papers:
ITGA3 is named in the same sentence as 121 diseases in open-access papers, as found by Europe PMC text mining. Sharing a sentence is not in itself a finding about the gene and the disease. The quoted sentences say what the papers report.
pancreatic cancer (24 papers, 2018 to 2025). "This study aimed to investigate the association of ITGA3 expression with pancreatic cancer (PCa) prognosis." (PMID 36561844, 2022). "Bioinformatics analysis revealed that the expression of ITGA3 can be used as a diagnostic and prognostic marker for pancreatic cancer, but its expression in GC is still unclear." (PMID 33335550, 2020). "More recently, in another study overexpression of ITGA3 has been associated with a poor prognosis in patients with pancreatic cancer and ablation of ITGA3 was reported to be accompanied by a significant decrease in the EGFR expression and tumour growth." (PMID 31953437, 2020). "Integrin Subunit Alpha 3 (ITGA3) gene has a close association with pancreatic cancer." (PMID 38305809, 2024). "Hence, ITGA3 has the potential to serve as a diagnostic marker and prognostic indicator for pancreatic cancer." (PMID 38305809, 2024). "Higher expression of ITGA3 in pancreatic cancer patients, particularly in early-stage cancer patients, is associated with poorer overall survival and recurrence-free survival." (PMID 38305809, 2024). "ITGA3 evidently promotes extracellular matrix remodeling and metastasis in pancreatic cancer, its expression is increased in a variety of tumors, and these events are closely related to tumor metastasis and poor prognoses." (PMID 37377917, 2023). "The present study indicated that ITGA2, ITGA3, ADAM9, and BHLHE40 were potential target genes associated with the development of pancreatic cancer." (PMID 37377917, 2023). "Using univariate Cox regression, a forest map was generated showing seven ARGs associated with pancreatic cancer prognosis: BAK1, ITGA3, BIRC5, WDR45, BAG3, APOL1, and RAB24." (PMID 35488119, 2022). "Studies have shown that ITGA3 can be used as a poor prognostic factor for pancreatic cancer, head and neck cancer and tongue squamous cell carcinoma." (PMID 34094951, 2021). "ITGA3 is highly expressed in bladder cancer, intrahepatic cholangiocarcinoma, pancreatic cancer, and nasopharyngeal carcinoma." (PMID 33335550, 2020). "Anti-tumor miR-124-3p regulates important intracellular pathways for pancreatic cancer via dual ITGA3/ITGB1." (PMID 29988949, 2018). "Interestingly, several studies have posited FN1 and ITGA3 as potential autonomous prognostic biomarkers for various diseases, including ovarian cancer, pancreatic cancer, oral squamous cell carcinoma, and breast cancer." (PMID 39114033, 2024). "Although the clinical value of this gene in thyroid cancer is undetermined, recent studies have revealed that ITGA3 plays an important role in multiple cancers; it is highly expressed in bladder cancer, pancreatic cancer, and endometrial cancer and was correlated with poor prognosis." (PMID 35174063, 2021). "Moreover, several studies have confirmed that ITGA3 is a marker of glioblastoma, pancreatic cancer, and thyroid cancer." (PMID 34631779, 2021). "Additionally, Itga3 has been shown to promote glycolysis through FAK phosphorylation in pancreatic cancer, suggesting that both genes may also significantly contribute to injury in MASLD donor liver transplantation and warrant further exploration." (PMID 41284206, 2025). "Moreover, several studies have shown that ITGA3 maintains aberrant expression in various types of cancer, including prostate cancer, intrahepatic cholangiocarcinoma, melanoma, pancreatic cancer, squamous cell carcinoma of the tongue, breast cancer, and colorectal cancer." (PMID 35563422, 2022). "In pancreatic cancer, it has been reported that high expression of ITGB1 is involved in the migration of cancer cells, and that high expression of ITGB1 and ITGA3 confers resistance to gemcitabine by increasing integrin α3β1 signaling." (PMID 35648752, 2022). "Out of 11 ITGA3, MET, FNDC3B, PPP1R14B and KIAA0513, including PLAU, were previously reported as individual prognostic markers in the pancreatic cancer TCGA-PAAD cohort." (PMID 36591282, 2022).
pancreatic cancer (continued). "BAK1, ITGA3, BAG3 and APOL1 were highly expressed in most pancreatic cancer and pancreatic ductal adenocarcinoma cell lines, while RAB24 was poorly expressed." (PMID 35488119, 2022). "The expression levels of BAK1, ITGA3, BAG3, and APOL1 were statistically increased in pancreatic cancer samples versus normal samples, while those of RAB24 was decreased." (PMID 35488119, 2022). "ITGA3 and ITGA6, both members of the integrin signaling pathway, are overexpressed in pancreatic cancer." (PMID 29764514, 2018). "However, in pancreatic cancer, downregulation of miR‐383‐5p by upregulation of FTO promotes cancer progression by upregulating the expression of integrin subunit alpha 3 (ITGA3), a target of miR‐383‐5p." (PMID 40448344, 2025). "ITGA3 expression negatively regulates stemness and EMT processes in breast cancer cells, though it was reported to promote metastasis and EMT plasticity in pancreatic cancer." (PMID 39085893, 2024). "ITGA3 expression was observed to be higher in pancreatic cancer patients compared to non-cancer patients and showed correlation with clinical traits such as histologic type, histologic grade, stage, T classification, and survival status." (PMID 38305809, 2024). "Some of them (ITGA3, CDK1, IFIT3, ANXA1, ANXA2, OAS1, and LACTB) have been studied to varying degrees concerning their relationship with pancreatic cancer." (PMID 36834681, 2023). "Notably, ITGA3 has been identified as a negative prognostic factor for pancreatic cancer, head and neck cancer, and tongue squamous cell carcinoma." (PMID 39070142, 2024). "Compared with those from the normal controls, immunohistochemical results from the pancreatic tissues revealed statistical increases in the expression of BAK1, ITGA3, BAG3, and APOL1 in pancreatic cancer patients; no immunohistochemical data were available for RAB24." (PMID 35488119, 2022).
breast carcinoma (23 papers, 2012 to 2025). "Further survival analysis showed that low expression of ITGA3 was significantly associated with poor RFS in breast cancer patients." (PMID 34094951, 2021). "In view of its prognostic value in BRCA, we used TCGA normal and breast cancer data to generate ROC curves to further analyze the diagnostic value of ITGA3 in BRCA." (PMID 34094951, 2021). "High expression of ITGA3 was associated with better prognosis of breast cancer patients." (PMID 34094951, 2021). "ROC curves showed that ITGA3 had significant diagnostic value for breast cancer, indicating that ITGA3 might be a potential diagnostic biomarker for BRCA." (PMID 34094951, 2021). "Integrin subunit Alpha 3 is essential for cell adhesion and movement, but its role in breast cancer (BC) is unclear." (PMID 40181838, 2025). "ITGA3 has the potential to serve as a predictive marker and therapeutic target for the treatment of breast carcinoma." (PMID 40181838, 2025). "ITGA3 also serves as a favorable prognostic biomarker and contributes to several types of cancers, such as breast cancer." (PMID 38702644, 2024). "To study their role in tumorigenesis, we first interrogated the TCGA database comprising the main molecular subtypes of breast cancer, for the expression of ITGA3 and ITGA6 transcripts." (PMID 38835038, 2024). "The expression of ITGA3 in normal breast tissues was greater than that in breast cancer tissues at both the mRNA and protein levels." (PMID 34094951, 2021). "Our additional observation that high ITGA3 expression was positively correlated with high BRN2 expression in basal-like breast cancer lends credence to the clinical relevance of our experimental findings that α3β1 induces Brn-2 expression in TNBC cells." (PMID 33513758, 2021). "The purpose of this study was to explore the significance of ITGA3 expression in the prognosis and clinical diagnosis of breast cancer patients." (PMID 34094951, 2021). "We studied the correlation between ITGA3 and immune cell infiltration in breast cancer by immune infiltration analysis, and the results showed that ITGA3 was significantly related to B cell and macrophage infiltration." (PMID 34094951, 2021). "Next, the Kaplan–Meier plotter database was used to evaluate the prognosis of ITGA3 in patients with breast cancer, ovarian cancer, lung cancer and gastric cancer, as well as the prognosis under different pathological subtypes." (PMID 34094951, 2021). "Correlation of ITGA3 mRNA expression and clinical prognosis in breast cancer with different subtypes by Kaplan–Meier plotter." (PMID 34094951, 2021). "From the PrognoScan database, high expression of ITGA3 showed favorable prognosis in breast cancer and eye cancer, and poor prognosis in colorectal cancer, lung adenocarcinoma, non-small-cell lung cancer and ovarian cancer." (PMID 34094951, 2021). "This study identified ITGA3 as a novel biomarker to estimate the diagnosis and prognosis of breast cancer." (PMID 34094951, 2021). "In conclusion, the expression of ITGA3 in breast tissues was higher than that in breast cancer tissues at both the mRNA and protein levels." (PMID 34094951, 2021). "By analyzing the expression level of ITGA3 in breast cancer, we found that the expression of ITGA3 was lower in breast cancer than in normal controls." (PMID 34094951, 2021). "On the one hand, immune infiltration analysis showed that in breast cancer, low expression of ITGA3 promotes B cell infiltration and M2 polarization." (PMID 34094951, 2021). "In line with this, luminal-like breast cancer cell lines form a clear cluster of low ITGA3 expression in both datasets." (PMID 31101121, 2019).
breast carcinoma (continued). "Together, these findings demonstrate that the absence of α3 promotes tumor growth and vascularization and strongly increases the invasive and metastatic potential of HER2-driven breast cancer, resulting in reduced overall survival of Itga3 KO mice." (PMID 31101121, 2019). "Together, these data indicate that HER2-driven, luminal-like breast cancer cells exhibit lower ITGA3 expression than triple-negative breast cancer cells." (PMID 31101121, 2019). "We have further used several established triple-negative and HER2-overexpressing human mammary carcinoma cell lines and generated ITGA3-knockout cells to investigate the role of α3β1 in vitro." (PMID 31101121, 2019). "For paclitaxel we found that three genes were reported to be associated with ovarian cancer (HOXB2, MYC, and TFPI2; p=0.024) and two genes were strongly associated with tumorigenesis of breast cancer (DUSP2 and ITGA3; p<0.001)." (PMID 29416679, 2018). "Interestingly, ITGA6 levels were significantly higher in basal-like tumors when compared with the other breast cancer subtypes, while ITGA3 levels were lower in this group." (PMID 38835038, 2024). "Epithelial.cells. is a favorable factor for survival and its top maker gene is ITGA3, which could regulate stemness and epithelial-mesenchymal transition of breast cancer cells." (PMID 38333684, 2024). "Next, we further explored the downregulationed mechanism of ITGA3 in breast cancer." (PMID 34094951, 2021). "In addition, tumor pathological stage showed that lower expression of ITGA3 was associated with poorer OS and RFS in stage 3, indicating that ITGA3 was related to the prognosis of patients with advanced breast cancer." (PMID 34094951, 2021). "Then, we analyzed the mechanism of ITGA3 in the prognosis of breast cancer patients." (PMID 34094951, 2021). "Here, we investigated the relationship between ITGA3 and TILs in breast cancer." (PMID 34094951, 2021). "Our research provides new directions and insights into the mechanism of ITGA3 in breast cancer and determined that ITGA3 may be a potential prognostic-related biomarker in BRCA, offering new ideas for clinical diagnosis and application." (PMID 34094951, 2021). "Moreover, BRN2 expression is significantly upregulated in patients with basal-like (i.e., triple-negative) breast cancer, where it also correlates with high expression of ITGA3 mRNA." (PMID 33513758, 2021). "Moreover, high BRN2 expression positively correlates with high ITGA3 expression in basal-like breast cancer, which is consistent with our experimental findings that α3β1 induces Brn-2 in TNBC cells." (PMID 33513758, 2021). "Here, we proved for the first time that ITGA3 exhibits promoter methylation in breast cancer." (PMID 34094951, 2021). "The up-regulation of ITGA2 and ITGA3 observed in this study in brain seeking breast cancer cell line 231BR may provide a potential indicator for breast cancer metastasis, and better understand the role integrin plays in this critical bioprocess." (PMID 31758065, 2019). "In addition, further correlation between ITGA3 and immune markers showed that ITGA3 could regulate the tumor infiltrating immune cell pattern in the tumor microenvironment of breast cancer." (PMID 34094951, 2021). "Therefore, low expression of ITGA3 leads to a poor prognosis for breast cancer patients." (PMID 34094951, 2021). "To assess α3β1 expression among breast cancer samples, we first performed immunohistochemistry on commercially available tissue microarrays (TMAs) using an antiserum specific for the integrin α3 subunit (ITGA3), or the corresponding preimmune serum from the same rabbit as a calibration control." (PMID 24950714, 2014). "MDA-MB-231 breast cancer cell lines express high levels of ITGA2 / ITGB1, ITGA3 / ITGB1, ITGA5 / ITGB1, ITGAV / ITGB3 integrins, compared to MCF-7, T47D, and ZR75-1 breast cancer cells." (PMID 25593998, 2014).